CD4 (CD4 molecule)
Diseases named in the same sentence as CD4 in open-access papers (continued):
Sharing a sentence is not in itself a finding about the gene and the disease.
COVID-19 (continued). "The CD4+ T cell population was maintained within the COVID-19 positive individuals where naïve, activated, and central memory CD4+ T cell subsets showed a significant increase upon SARS-CoV-2 infection." (PMID 37886355, 2023). "In COVID-19, increased levels of IL-6 support the differentiation of pro-inflammatory Th17 cells and a decrease of the T cells, such as CD4+ T cells, CD8+ T cells and natural killer (NK) cells." (PMID 36941580, 2023). "People with HIV with low CD4 cells count or detectable HIV-RNA seem to have an increased risk of severe COVID-19, while people with an undetectable HIV-RNA and a CD4 count higher than 200 cells/mm3 appear to have the same risk as people without HIV." (PMID 37243000, 2023). "In contrast, the subdominant DR15/S236+CD4+ memory T cells population exhibits a more Tnaive memory phenotype profile in COVID-19 convalescent patients." (PMID 36969254, 2023). "Bronchoalveolar lavage fluid CD4+ T cells of patients with COVID-19 were TH1-skewed and showed de-repression of genes downregulated by Vitamin D which notably activates the recruiting of c-JUN and switches on the pro-inflammatory programs of TH1 cells." (PMID 37877121, 2023). "As an extrapolation of these findings, B-cells subsets have also been studied in individuals with hematologic malignancies and COVID-19, showing that mortality in these patients was closely related to defects in CD4+ and B-cells quantifications." (PMID 37897014, 2023). "In mild COVID-19 patients' CD4 subset, Th EM-Tim-3+ (Median 3.3; Q1-Q3 2.45-5.6.3) population was significantly higher as compared to controls (Median 0.5; Q1-Q3 0.3-0.85; p=0.002)." (PMID 37465793, 2023). "In summary, we present a detailed investigation into the breadth of the single-peptide NSP12 CD4+ T-cell response in a cohort of COVID-19 patients with known HLA backgrounds." (PMID 37215095, 2023). "MK has been shown to regulate and interfere with the activity of both CD8+ and CD4+ T cells, indicating a possible role for MK in the progression of COVID-19." (PMID 37835544, 2023). "Given the complex interplay between HIV and COVID-19, more prospective studies investigating the factors such as the contribution of viral burden, CD4 cell count, and the details of patients’ anti-retroviral therapeutic regimens should be pursued." (PMID 37509543, 2023). "Nevertheless, CD4+ and CD8+ T-cell immunity against BA.1 induced by prior infection with SARS-CoV-2 ancestry virus and other variants or by COVID-19 vaccines was relatively conserved." (PMID 36992306, 2023). "CD4+ T-cell profiles in convalescent coronavirus disease-19 (COVID-19) patients at 3 months post admission." (PMID 37310006, 2023). "A significant decrease of CD4 and CD8 cells in severe COVID-19 patients vs. controls (CD4, median 49; CD8, 40.12; p>0.05) was seen." (PMID 37465793, 2023). "We detected a higher percentage of antigen reactive CD4 T cells in individuals that recovered from COVID-19 with mild local symptoms as compared to asymptomatic disease courses, and highest in individuals with fever." (PMID 37313411, 2023). "Using set analysis within the ISB-S CD4 dataset, we found that the motif-based clustering of T cells via GLIPH2 algorithm successfully identified 677 CD4 T cell clusters that are common across all levels of severity of COVID-19." (PMID 36670287, 2023). "Yet, in another study, COVID-19 convalescent patients had fewer neutrophils, higher expression of cytotoxic CD4 and CD8 T cell (e.g., HLA-DR and CD38), and B cell markers ten weeks after disease onset compared with heathy controls." (PMID 37483545, 2023). "Compared to CD4+ and CD8+ T cells, SARS-CoV-2-specific CD4+ T cells showed a strong correlation with reduced COVID-19 severity." (PMID 36901827, 2023). "The COVID-19-enriched effector CD4 T cell population had a separate trajectory from other effector CD4 T cells, rather running in parallel to Tregs due to their relative phenotypic similarity." (PMID 36669118, 2023).
COVID-19 (continued). "The DR15/S751-specific CD4+ T cells frequency was detected by tetramer technique up to 1.36×10-4 in early convalescent patients from mild to moderate COVID-19, which was 34-fold higher compared to uninfected individuals." (PMID 36969254, 2023). "Of the COVID-19 patients, 81% (22 out of 27) and 92% (13 out of 14) of the seronegative controls showed peptide-specific CD4+ T-cell responses to at least one NSP12 peptide specificity." (PMID 37215095, 2023). "CD4+ T cells of patients with severe COVID-19 appear to be TH1-skewed and show de-repression of genes that are downregulated by vitamin D, from either lack of substrate (a low vitamin D state) or abnormal regulation of this system." (PMID 37447302, 2023). "Recent evidence demonstrated that asymptomatic COVID-19 individuals have highly multifunctional SARS-CoV-2-specific T cell responses, and coordinated and robust CD4+ and CD8+ T cell immunity are associated with milder disease." (PMID 36969254, 2023). "The majority of these NSP12 peptide-specific T-cell responses were CD4+ T-cell responses, as has been described for the T-cell response directed human COVID-19 T-cell response directed against other SARS-CoV-2 proteins." (PMID 37215095, 2023). "COVID-19 patients with mild-moderate severity who recovered quickly have a statistically higher amount of T cells, CD4+ cells, and CD8+ cells." (PMID 37377785, 2023). "Overall, we found a broadly directed, low-level NSP12-specific CD4+ T-cell response in COVID-19 patients, with a higher magnitude in the acutely infected patients." (PMID 37215095, 2023). "In the analysis of the GSE201530 dataset with the “CIBERSORTx” tool, we observed a significant increase in the proportion of monocytes, activated memory CD4 T cells and resting mast cells in COVID-19 patients." (PMID 37630661, 2023). "Another difference is that CD4+ T cells from convalescent patients from mild to severe COVID-19 are in an activated state." (PMID 37153606, 2023). "It is reported that virus infection increases the ER stress which further enhances unfolded protein response (UPR) to neutralize the detrimental effect and restore ER homeostasis which is also evident in COVID-19 patients in activated CD4+ T cells." (PMID 37886355, 2023). "The hallmark of both CD4+ and CD8 + T cells in COVID-19 lungs was broad PD1 expression, together with CD16." (PMID 36774347, 2023). "Patients with severe COVID-19 have shown a significant reduction in levels of lymphocytes, monocytes, CD4+T cells, CD8+T cells, CD3 cells, CD19 cells, and natural killer cells." (PMID 37764085, 2023). "Severe COVID-19 has been associated with increased CD8+ T cell activation and suppression of naïve CD4 T cells." (PMID 38292490, 2023). "Almost all COVID-19 patients develop a T cell response, which is more prominent in the CD4+ compartment than in the CD8+ compartment." (PMID 36875071, 2023). "In CD4+ Th-cell compartment, the percentage of the central memory population was found to be significantly high in the vaccinated Omicron COVID-19 patient group compared to the uninfected controls (p < 0.05)." (PMID 37881339, 2023). "A later study proved that the acute immunodeficiency character of COVID-19 stems from the immunoparesis of the CD4+ T-cell pool, and can also be demonstrated by peripheral T-cell exhaustion." (PMID 37568402, 2023). "recently reported the significance of T cell responses to SARS-CoV-2 in specific antibody production by showing that spike-specific CD4+ T cell responses correlated with the magnitude of specific IgG titers in recovered COVID-19 patients." (PMID 37564647, 2023). "Another observation was an expansion of activated CD4+ T and NK T cells in the COVID-19 positive individuals that was further reduced in recovered individuals." (PMID 37886355, 2023).
COVID-19 (continued). "Within CD4+ T cell meta2cells, this analysis revealed a fine-grained trajectory of phenotypes enriched in patients with critical COVID-19, with T cell phenotypes that correspond meaningfully with disease stage." (PMID 36973557, 2023). "Similar to CD8 cells, evidence is that CD4 cells exhibit functional impairment and elevated expression of activation and/or exhaustion markers in COVID-19 patients." (PMID 37465793, 2023). "Studies on COVID-19 patients suggest alterations in CD4 and CD8 cell counts, indicating apoptosis and lymphocytopenia." (PMID 37515156, 2023). "Vaccinated individuals have also been reported to develop higher levels of CD4+T cell activation than recovered COVID-19 patients." (PMID 37228604, 2023). "The CD4+ T cell population from COVID-19 lungs showed higher expression of CD8 and cytotoxicity-related markers." (PMID 36774347, 2023). "With respect to vaccine-induced immunity, most of the available COVID-19 vaccines consist of a single antigen, restricting epitope breadth of CD4+ and CD8+ T-cell responses compared with natural infection." (PMID 36830907, 2023). "Egger’s test detected the existence of publication bias in potential predictors for seroconversion due to COVID-19 vaccines, including the CD4 T-cell counts (p < 0.01) and HIV viral load (p = 0.02)." (PMID 37112701, 2023). "This study aimed to reveal the influence of extending the inoculation interval on the humoral immunity induced by the third dose of the inactivated COVID-19 vaccine in PLWH with a CD4 count < 500 cells/μL." (PMID 36936952, 2023). "Namely, studies in adults have shown that milder cases of COVID-19 correlate with lower CD4+ T-cell responsiveness and higher CD8+ T-cell responsiveness." (PMID 38193077, 2023). "SARS-CoV-2-specific central memory (CCR7+, CD45RA−) TH1 CD4+ T cells persist in patients recovered from COVID-19 with an estimated half-life of ∼200 days; TH2 and TH17 cells do not contribute significantly to this memory pool." (PMID 37471227, 2023). "At the 20-month follow-up, most participants (92 of 93) had received COVID-19 vaccinations and the frequency of S-specific CD4 + T cells had increased to levels comparable to 1 month after infection." (PMID 37974069, 2023). "Previous clinical findings indicate that lymphocyte measurements including B cells, natural killer (NK), CD8+ cytotoxic T and CD4+ T cells were all reduced in COVID-19 patients." (PMID 37767093, 2023). "In conclusion, our study demonstrates that the senescence of CD4 and CD8 T-cells is negatively associated with poor specific COVID-19 vaccine-induced immunity." (PMID 37334387, 2023). "CD4+ T cells are hyperactivated in severe COVID-19 patients, although Foxp3 expression is suppressed." (PMID 36992283, 2023). "Amongst HIV-1 uninfected patients with COVID-19 there was a significant trend towards a lower percentage of lymphocytes positive for CD4 and CD8 with increasing WHO grade severity." (PMID 36635274, 2023). "On the contrary, recent studies presented on CROI 2022 reported the worst COVID-19 clinical outcomes in PLWH with recent CD4+T cell counts of <200." (PMID 37243203, 2023). "Our work identified that CASP1, CD4, and EIF2AK3 were diagnostic genes of COVID-19 and correlated with immune activity." (PMID 37228369, 2023). "The HLA-II peptide LSYYKLGASQRVAGD identified in this study was previously found to be recognized by CD4+ T cells in twelve COVID-19 patients." (PMID 36992131, 2023). "The expression of IL6R was shown to be higher in COVID-19 patients activated CD4+ T cells, naïve T cells, and DCs when compared to healthy controls." (PMID 36769328, 2023). "Lymphopenia has been described in many patients with COVID-19, primarily characterized by lowered CD4+ and CD8+ T-cell counts also observed in several coronavirus infections." (PMID 37626620, 2023). "The presence of CD4+ T-cell lymphopenia was found to be a reliable predictor of severity and hospitalization in COVID-19 individuals." (PMID 36980393, 2023).
COVID-19 (continued). "mRNA COVID-19 vaccines generated functional memory B cells that increased from 3 to 6 months post-vaccination and further induced antigen-specific CD4+ and CD8+ T cells, and early CD4+ T cell responses." (PMID 36680026, 2023). "Data analysis revealed a statistically significant difference in IFN-γ secretion across the three time points when comparing the median differences of CD4+ T-cell responses to COVID-19 (Ag1) (X2 = 6.138, p = 0.046)." (PMID 37515127, 2023). "The reduction of CD8+ T cells and B cells and the consequent increase in the CD4/CD8 ratio has been reported in numerous cases of critically ill patients with COVID-19." (PMID 37035317, 2023). "The abundance of plasma cells, CD4+ naïve T cells, CD4+ memory-activated T cells, γδT cells, and resting dendritic cells was significantly higher in the COVID-19 group compared to the control group." (PMID 38384322, 2023). "S13, respectively) showed an increase in percentage of CD8+ T cells and a decrease in percentage of CD4+ T cells in COVID-19 convalescent patients compared to the controls (P = 0.036)." (PMID 37824612, 2023). "Considering the potential predictive value of the CD4 T-cell counts in seroconversion due to the COVID-19 vaccines in PLWH, univariate meta-regression and subgroup analyses were further carried out to explore the source of heterogeneity." (PMID 37112701, 2023). "We compared the distribution response pattern of the peptide-specific CD4+ T-cell responses with respect to the location within the NSP12 in protein in COVID-19 patients and seronegative individuals." (PMID 37215095, 2023). "SARS-CoV-2 infection induced cytokine overexpression in hospitalized patients with COVID-19 as well as lymphopenia, particularly a decrease in CD4+ and CD8+ T cell counts." (PMID 37483627, 2023). "Bioinformatics prediction and mass spectrometry were used to determine the SARS-CoV-2 peptide sequences in HLA-I and HLA-II peptidomes that are specifically recognized by circulating the CD8+ and CD4+ T cells of COVID-19 patients." (PMID 36992131, 2023). "CD4+CD25+ cells were significantly higher in the acute phase of COVID-19, as a percentage of total lymphocytes, in participants who later developed persistent forgetfulness when compared to those who did not (p<0·01)." (PMID 38327763, 2023). "In contrast with severe COVID-19 symptoms, dysregulation of immunity CD4, CD8 T cells and regulatory T cells is exclusively correlated with the severity of COVID-19 infection." (PMID 37766091, 2023). "Myeloid-derived suppressor cells and cytotoxic CD4+ T-cells are two characteristics of severe COVID-19 that are still present in PASC." (PMID 38203577, 2023). "CD4 signaling in monocyte was previously suggested to promote their differentiation into macrophages and phagocytosis while CD4+ monocyte were reduced in COVID-19." (PMID 37488118, 2023). "In this study, the expression level of CD4+CD25+Foxp3+ T-regs was higher in COVID-19 patients than healthy controls." (PMID 38139439, 2023). "FACS analysis of T cell subsets revealed a trend of increasing percentage CD4+ T cells subsets with increasing disease severity, with the highest percentage being in stage IV of COVID-19." (PMID 37057213, 2023). "In line with this, it has been reported that S-specific T cell response, elicited by SARS-CoV-2 infection, was dominated by the CD4+ subset in COVID-19 patients." (PMID 36817441, 2023). "In acute COVID-19 cases, rapid activation of SARS-CoV-2-specific CD4+ T cells was shown to cause milder symptoms with faster viral clearance." (PMID 36901827, 2023). "A higher neutrophil-to-CD8 ratio has been considered a predictor of a severe COVID-19 course, while increased CD4-to-CD8 T cell ratio serves as a good prognostic marker for disease severity with mortality prediction power." (PMID 37835544, 2023). "Presence of SARS-CoV-2-specific CD4 and CD8 T cells were found to be associated with a decreased severity of COVID-19." (PMID 37920457, 2023).
COVID-19 (continued). "It is noteworthy that our results provide further evidence linking KD with COVID-19, as all three CD4+ T cell clusters from KD patients were found to cluster within the COVID-19 signaling pathway." (PMID 37841239, 2023). "Lymphopenia was seen in moderate to severe cases of COVID-19 with a drastic reduction of CD4 and CD8 T cells count." (PMID 37107714, 2023). "In COVID-19, as in many other viral infections, CD4+ T cells are crucial for providing help to CD8+ T and B cells." (PMID 36875071, 2023). "In our study, severely ill COVID-19 patients had greater frequencies of CD4+ T cells co-expressing CD62L and immune checkpoint markers, specifically PD-1 and CTLA-4." (PMID 36817450, 2023). "In the present study, a significant increase was observed in the population of CD4+ T cells, including activated HLA-DR+CD4+ T cells, among patients with mild-to-moderate COVID-19 who were treated with demeclocycline." (PMID 37612352, 2023). "In conclusion, our study indicated that PLWH with lower CD4 cell count showed a weaker humoral immune response to inactivated COVID-19 vaccination, especially those with CD4 cell count < 200 /μL." (PMID 36670363, 2023). "This signature points to a CD4+ cytotoxic phenotype and indeed virus-reactive CD4+ cytotoxic cells were described to be increased in blood during COVID-19." (PMID 37730638, 2023). "In a recent study, the researcher examined long COVID-19 patients and discovered that the number of naïve CD4+ T cells was similar in long COVID-19 and healthy, recovered individuals." (PMID 37766091, 2023). "Similar to our ex vivo experiments, SARS-CoV-2 RNA was detected in CD4+ T cells from COVID-19 patients." (PMID 37523305, 2023). "A significant shift in clusters within phenotypically naïve CD4 cells was also observed in COVID-19 patients." (PMID 36669118, 2023). "Using publicly available single-cell RNA sequencing (scRNAseq) data, we detected the presence of SARS-CoV-2 RNA in 2.1% of CD4+ T cells of the bronchoalveolar lavage (BAL) of patients with severe COVID-19." (PMID 37523305, 2023). "The authors did not observe significant differences between patients with mild or severe forms of COVID-19 and controls for CD4." (PMID 37046564, 2023). "To determine if these differences held across the spectrum of disease severity, we next performed a differential gene expression analysis of spike-specific CD4+ T cells sampled on day 35 and at 6–9M and 18M after mild or severe COVID-19." (PMID 38064569, 2023). "We also found that spike-specific and nucleocapsid-specific CD4+ T cells were more polyfunctional after severe versus mild COVID-19." (PMID 38064569, 2023). "It has been shown that COVID-19 patients had reduced CD4+ and CD8+ T cell counts in peripheral blood." (PMID 36675642, 2023). "of immune phenotypic singularities in COVID-19 patients, such as the lower representation of TREGs as well as the increase of the CD4-CTL and cytotoxic TFH subsets – especially in severe presentations of the disease." (PMID 37388738, 2023). "Drawing on insights gleaned from prior research, it becomes evident that discrepancies in the percentage and behavior of CD4+ or CD8+ T cells are characteristic of COVID-19." (PMID 38004749, 2023). "Our study supports the finding of a previous study, which discovered a strong correlation coefficient between CD4+ in peripheral blood and total lymphocytes in COVID-19 patients (r = 0.9051, p < 0.01)." (PMID 37377785, 2023). "On the other hand, lower CD4+ or CD8+ frequencies were detected in severe COVID-19 patients compared to mild COVID-19 patients." (PMID 36839596, 2023). "For 2020 when COVID-19 cases and lockdown measures were introduced, a monthly median CD4 range of 39 (IQR: 15–70) to 45 (IQR: 19–70) was reported." (PMID 37768950, 2023). "Decrement in percentage of CD4+FoxP3+ Tregs in peripheral blood of COVID-19 patients in terminal stage of disease is in line with lower systemic TGF-β, one of the major products of Tregs." (PMID 37057213, 2023).